CCR7 (C-C motif chemokine receptor 7)
Diseases named in the same sentence as CCR7 in open-access papers (continued):
Sharing a sentence is not in itself a finding about the gene and the disease.
tumor (continued). "For example, pre-clinical studies have demonstrated that CCR7 expression in tumor cells promotes migration towards lymphatic vessels, LVI, and LN metastasis." (PMID 34685565, 2021). "It is reported that the expression levels of CX3CR1, CXCR4, CXCR5, and CCR7 in tumor tissues are significantly increased, which is able to affect the survival time of patients." (PMID 34603645, 2021). "Epidermotropism and tumor growth within the skin environment of SS are features that had been attributed to CCR7 function, but the exact mechanisms are poorly characterized." (PMID 34778050, 2021). "In mice, it was shown that tumours can produce LXR ligands that block expression of CCR7, which prevents DCs undergoing maturation to migrate to lymph nodes around the tumours." (PMID 34086048, 2021). "For example, Rizeq’s study found that activation of the C–C chemokine receptor 7 (CCR7)-related complex increased tumor cell proliferation and migration." (PMID 34507558, 2021). "This increases their homing behaviour and drives tumor growth and metastasis, particularly towards lymphatic organs, where the two ligands of CCR7, CCL19 and CCL21, are constitutively expressed." (PMID 34575965, 2021). "Accordingly, an in vivo study showed that tumor cells with high expression of CCR7 had higher metastatic potential in the lymph node of the heterotopic transplantation mouse model." (PMID 33390169, 2021). "Much like CCR5, CCR7 is a chemokine receptor present in certain subsets of immune cells that can be pathologically expressed by tumor cells." (PMID 34575965, 2021). "Both cDC1s and cDC2s were shown to take up tumor antigens and to migrate to tumor draining lymph nodes in a CCR7-dependent manner." (PMID 32486257, 2020). "The priming of CD8+ T cells by cDC1s has been described to happen in the tdLNs after CD103+ cDC1s take up the tumor antigen, upregulate CCR7 on their surface to home to the lymph node, where they then cross-present antigen to LN-resident CD8+ T cells." (PMID 33268774, 2020). "In fact, CXCR4, SPP1, ACKR3, CCL2, PTGS2, CD274 (PD-L1), CXCL11 were upregulated while CCL28, CCR1, CCR7 were down regulated in both comparisons (blue boxes), suggesting this as a signature specific of the core region of the tumor." (PMID 33066172, 2020). "This suggested that m1928z-CD40L CAR T cell treatment recruits DCs to the spleen and tdLNs by inducing upregulation of CCR7 on tumor-resident DCs." (PMID 33268774, 2020). "Recently, the expression of CXCR4 and CCR7 have received considerable attention in tumor cells for their direct involvement in metastasis." (PMID 32340161, 2020). "Early seeding via the blood stream requires the expression of the homeostatic chemokine receptor CCR7 and of L-selectin, both cooperate to facilitate transmigration of tumor and also of protective tumor-reactive lymphocytes via HEV structures." (PMID 33343570, 2020). "Targeting CCR7 with a mAb inhibited ligand-mediated signaling pathways and induced tumor cell killing in primary samples." (PMID 33110606, 2020). "In conclusion, the present study demonstrated that the expression levels of CXCR4, CXCR5 and CCR7 were significantly higher in tumor tissues." (PMID 32896997, 2020). "To better represent a clinical scenario for an anti-CCR7 treatment, we used a post-implantation set-up in which tumor cells had migrated to their target organs and niches." (PMID 33110606, 2020). "As a member of the C-C-like chemokine receptor family, CCR7 participates in the regulation of tumor cells including tumorigenesis, proliferation, invasion, and metastasis." (PMID 33158173, 2020). "CCR7 is highly expressed in villous and cancers, affecting the migration and invasion of trophoblast and tumor cells." (PMID 32719429, 2020). "Hematopoietic and non-hematopoietic tumors metastatic to lymph nodes are correlated with tumor-dependent CCR7 expression." (PMID 32340161, 2020).
tumor (continued). "In NSCLC, a study observed an upregulation of CXCL9/CCR7 in tumor tissue, especially in patients with metastasis to lymph nodes." (PMID 32974144, 2020). "As the chemokine receptor CCR7 is a molecule expressed in a wide range of malignancies and relevant in many tumor processes, the present study addressed the biologic role of this receptor in T-PLL." (PMID 33110606, 2020). "For instance, CCR7+ tumor cells will preferentially traffic toward CCL21 secreted by lymphatic endothelial cells (LECs), promoting initial metastasis through the lymphatic system." (PMID 32002106, 2020). "A further decrease of CCR7 expression was observed in tumor-infiltrating CD8+ Tc cells when compared to peripheral blood of tumor patients (p = 0.06)." (PMID 32082401, 2020). "We were able to confirm the previous findings of decreased CCR7 expression on CD8+ Tc cells in tumor patients." (PMID 32082401, 2020). "For the initial priming of CD8+ CTLs tumor antigens must be delivered to tumor-draining lymph nodes by migratory CD103+ cDC1s in a CCR7-dependent manner." (PMID 32486257, 2020). "CCR7 takes part in chemotaxis, survival, migratory speed, cytoarchitecture, and endocytosis of DCs, which are closely related to tumor metastasis." (PMID 33303760, 2020). "In tumorigenesis, most studies emphasized on the relationship of CXCL9/CCR7 with tumor angiogenesis and metastasis." (PMID 32974144, 2020). "It has been reported that CCR7 facilitates cancer progression by manipulating cancer cells’ anoikis and mobility as well as controlling the tumor microenvironment, including the inflammatory responses, immune tolerance and T cell activation." (PMID 32340161, 2020). "Tumor-derived oxysterols were shown to inhibit DC trafficking to draining lymph nodes by downregulating CCR7 expression." (PMID 32486257, 2020). "cDC trafficking to the lymph node and generation of a systemic anti-tumor immune response is governed by CCR7 expression." (PMID 32508825, 2020). "The chemokine receptor CCR7 is a key protein involved in the metastasis of tumor cells to sentinel lymph nodes where there is an abundance of its ligand CCL21." (PMID 32872485, 2020). "NSCLC cells express the C-C chemokine receptor type 7 (CCR7), and CCR7 expression-positive tumor cells are preferred to their ligand-enriched lymphatic organs, providing a basis for the priority transfer of tumor cells to specific sites." (PMID 33158173, 2020). "All these studies indicate that CCR7 plays a complicated role in tumor progression and further studies are warranted to identify its actual function in NSCLC." (PMID 32896997, 2020). "Within gastric cancers, CCR7 expression in the primary tumor was reported as the most important factor in determining lymph node metastasis." (PMID 32340161, 2020). "Participation in cancer cell invasion, metastases and tumor development was reported with the CC Chemokine receptor 7 (CCR7)." (PMID 32340161, 2020). "LXRα agonists secreted by tumor cells can similarly promote tumor growth by blocking CCR7-mediated migration of cDCs from the TME to tumor-draining lymph nodes (TDLNs)." (PMID 32121071, 2020). "For example, a low level of CCL21 expressed in LAMP3+ DCs hinders CCR7+ cells, which facilitates tumor growth and indicates an unfavorable prognosis for HCC patients." (PMID 33225985, 2020). "The human MTCs and the DCs, functioning as APCs, both expressed the chemokine receptor CCR7 in the tumor." (PMID 32155856, 2020). "To further characterize CCR7 expression we also compared surface levels in our T-PLL cohort to the expression in different non-tumor T-cell subsets including CCR7-expressing TN and TCM cells (in both CD3+CD4+ and CD3+CD8+ subsets)." (PMID 33110606, 2020). "Pre-clinical studies have demonstrated that CCL19/CCL21 producing lymphatic endothelial cells can actively guide the chemotactic migration of CCR7-expressing tumor cells." (PMID 32340161, 2020).
tumor (continued). "To evaluate the in vivo anti-tumor efficacy of the anti-CCR7 mAb, first we used as hosts the RAG2−/−γc−/− strain, which lacks T, B, and functional NK cells, but has complement activity, thus allowing in vivo testing of the MOA characterized in vitro." (PMID 33110606, 2020). "Afatinib inhibited LYVE-1, VEGFR2, VEGFR3, VEGFC, VEGF, and CCR7 expression in a dose-dependent manner in HCC827 xenograft tumour tissues, and these results demonstrated the anti-lymphangiogenic action of Afatinib." (PMID 31892990, 2020). "Further, CD103+ or CD141+ DCs in mice or humans are critical to transport tumor cargo to draining lymph nodes in a CC chemokine receptor 7 (CCR7) dependent manner." (PMID 32674488, 2020). "In this regard, anti-CCR7 showed here to be effective in eradicating tumor cells from several localizations, including LN and CNS." (PMID 33110606, 2020). "In vivo studies show the knockdown of CCL21 in secondary lymphoid organs leads to the decrease of metastatic tumor formation, since this reduces both the chemotactic and antiapoptotic effects of CCR7-expressing tumor cells." (PMID 31555130, 2019). "The secretion of CCL21 by LECs, which drives CCR7-dependent tumor migration through LVs, is also enhanced in response to VEGF-C." (PMID 31024552, 2019). "In a tumoral context, CCR7 expression by DCs is primordial for their migration into tumor draining LNs and subsequent T cell activation." (PMID 31024552, 2019). "CCL21 plays a crucial role in the establishment of a tolerogenic tumor microenvironment by recruiting CCR7+ regulatory T cells in primary tumors and by promoting the formation of lymphoid like stromal structures with immunosuppressive features." (PMID 31024552, 2019). "The result showed that miR-532-3p was down-regulated and C-C chemokine receptor 7 (CCR7) was up-regulated in the tumor tissues compared with those in the paired paratumor tissues." (PMID 31555130, 2019). "In ACT, terminally differentiated CD45RA+ CCR7− T effector-like cells (TEff cells) demonstrated enhanced in vitro anti-tumor activity, whereas in vivo T cell activation, proliferative capacity, and persistence were impaired." (PMID 31835562, 2019). "We showed that the DCs which were pulsed with tumour-specific lysate and matured with full cocktail expressed high levels of CCR7." (PMID 30283982, 2019). "Expression of C-C chemokine receptor 7 (CCR7) by DCs is important for their trafficking to tumour-draining lymph nodes." (PMID 31776331, 2019). "Although generally excluded from peripheral tissues, naïve CD8+ T cells infiltrate CCR7-dependently and are activated in tumor mass, which represents—in spite of the numerous immunosuppressive mechanisms—an attractive site of T cell priming." (PMID 31396219, 2019). "In melanoma models, CCR7 expression in cDC1s was necessary for the trafficking of TAAs toward lymph nodes, where effector T cell priming occurred and triggered anti-tumour responses." (PMID 31776331, 2019). "CCR7 is also expressed by tumor cells, and the CCL21–CCR7 axis appears to mediate lymph node metastasis in different types of cancer." (PMID 30736372, 2019). "As a result, increased ratio of pro-apoptotic to anti-apoptotic gene expression undermines the immortality of tumor cells, while the reduced level of CCR7 and CXCR4 compromises their migratory capability." (PMID 31507423, 2019). "CCL21 is a chemokine that is present in humans and has an important role in mobilizing normal immune cells in response to tumor cells metastasizing to lymph nodes, via activation of a G protein-coupled receptor, CCR7." (PMID 31824269, 2019). "The role of chemokines in tumor angiogenesis was achieved in a CCR7-dependent manner through inhibiting Met/ERK/Elk-1/HIF-1α/VEGF-A pathway in CRC." (PMID 31214045, 2019). "We observed that CD103 + dendritic cells had indeed upregulated CD86 and CCR7 within the tumor after 12 h, and observed a corresponding increase in activation and accumulation within the draining lymph node at 48 h." (PMID 30718505, 2019).
tumor (continued). "Chemokines and chemokine receptors involved in this phenomenon are several: CCR7 mediates the migration of tumor cells to lymph nodes where their ligands, CCL19 and CCL21, are produced." (PMID 30894861, 2019). "In a mouse model of breast cancer, it was also shown that CCL21 recruits CCR7-expressing ILC3s with an LTi phenotype (CD4+CCR6+) to the tumor environment." (PMID 31507605, 2019). "VEGF-C has been shown to upregulate CCL21 expression by LECs, driving CCR7-dependent tumor chemoinvasion toward lymphatic vessels." (PMID 31105685, 2019). "Recent extension of these observations has shown a role for VEGF-C-induced CCL21 in the tumor infiltration of naive T cells prior to immunotherapy via CCR7-dependent chemotaxis." (PMID 31105685, 2019). "On day 13, we found a higher percentage and an increased number of CCR7+ migratory DCs in the tumor of mice treated with mH or mH/αCD4 (p < 0.05), relative to the mice without mH treatment." (PMID 30696484, 2019). "Previous reports described that CCR7 is essential for the DC trafficking from the tumor to draining lymph nodes." (PMID 30696484, 2019). "In HNSCC, elevated CCR7 expression is found to correlate with lymph node metastasis and tumour tissue histological differentiation status." (PMID 30417146, 2018). "The interaction of tumour cells with lymphatic cells can be promoted by interstitial fluid (resulting from lymphatic drainage) via autologous chemotaxis involving the chemokine CCL-21 and its receptor, CCR-7, expressed by tumour cells." (PMID 30406137, 2018). "CCR7 plays a role in the migration of tumor cells such as immune cells into lymphoid organs through binding to its only two ligands CCL19/CCL21." (PMID 30233771, 2018). "In several studies, CCR7 expression by IBC cells has been found to induce tumor growth, proliferation and metastasis, as well as angiogenesis and lymphangiogenesis in animal models." (PMID 30213113, 2018). "We then checked the expression of the chemokine receptor CCR7 that binds to the lymphatic attracting chemokine CCL21 in tumor infiltrating OT1 T cells." (PMID 30258446, 2018). "Accordingly, enrichment in CD56dim CCR7+ KIR+ CD57+ highly cytotoxic NK cells has been documented in tumor-infiltrated lymph nodes of melanoma patients." (PMID 30364222, 2018). "In the study, a positive association was found between high membrane and total CCR7 expression, and the presence of FOXP3+ tumor infiltrating cells in the adjacent stroma, as well as a trend for higher intratumoral FOXP3+ cells." (PMID 30213113, 2018). "This can be also explained as a hijack of physiological chemokine driven leucocyte migration by CCR7 in lymphatic migration of tumor cells during metastasis." (PMID 30417146, 2018). "Since the control group was chosen out of tumor-adjacent normal tissues and both groups were matched for age, so Chi-square test was used to analyze this section and compare the CCR7 marker expression in the two groups." (PMID 30233771, 2018). "Notwithstanding, Th22 cells, expressing high levels of CCR7, support tumor progression and have been shown to infiltrate colon and pancreatic cancers and hepatocellular carcinomas." (PMID 30591657, 2018). "Thus, also in the absence of pathogen-derived stimuli, the action of MMPs (or other still unknown mechanisms), may allow IL-18 shedding from TAM and the induction of CCR7 expression in CD56dim tumor-associated NK cells (TA-NK), thus promoting their migration to SLO and TLS." (PMID 30364222, 2018). "CCL21 is expressed in secondary lymphoid organs, binds to CCR7 and facilitates lymphatic invasion of tumor cells." (PMID 30018456, 2018). "They showed overexpression of functional CCR6 and CCR7 on metastatic tumor cell lines obtained from the liver." (PMID 30004409, 2018). "The same group of authors then demonstrated that Pyk-2 acts as an important downstream signaling player of the CCR7 pathway in SCCHN by regulating CCL19 dependent tumor cell migration, metastasis and viability." (PMID 28858212, 2017).
tumor (continued). "CC‐chemokine receptor 7 (CCR7) was confirmed to participate in cancer cell metastasis 12, invasion 13, and tumor development." (PMID 28378417, 2017). "In recent studies, the association between tumor progression, metastasis and inflammatory mediators TNF-α, IL-6, vascular endothelial growth factor (VEGF) and C-C motif chemokine receptor 7 (CCR7) have also been investigated." (PMID 29299026, 2017). "Although CCR7 regulates Notch1 activation in MMTV-PyMT tumor cells, the two pathways likely cooperate to promote CSC activity." (PMID 28137279, 2017). "Among them are cancer-related genes such as MYB and TGFBR1 as well as many immune-related genes such as CCR7 and FCRL3, whose prognostic association is likely to reflect the inflammatory process and the presence of lymphocytic cells in the tumour." (PMID 28059167, 2017). "In this contest, TCMs represent an effector-T-cell subset with long term memory and high tumor killing activity, which are able to achieve distant lymph-nodes and tumor sites due to the expression of chemokine receptors (CCR)-7 on their surface." (PMID 29100279, 2017). "This confirms the anti-adhesive effect of podoplanin in the tumor microenvironment and its role in favoring CCR7+ carcinoma cell movement and mediating escape." (PMID 28416768, 2017). "Patients’ baseline lymph node involvement status was also correlated and four patients who developed PD due to new lymph node metastasis all represented high CCR7 staining for their tumor tissues." (PMID 28114889, 2017). "A PDPN expressing model of CAFs made it possible to demonstrate the same CCL21/CCR7 axis involvement in the tumor cells to CAFs recognition mechanism through PDPN binding of CCL21." (PMID 28416768, 2017). "The results indicated that TNF-α can increase the lymph node metastasis of orthotopic xenograft tumours in nude mice, and this effect was impaired when CCR7 was silenced." (PMID 27009073, 2016). "A mechanism of this targeted migration was traced to the capacity of TGF-β1 to promote CCR7/CCL21-mediated crosstalk between tumor cells and lymphatic endothelial cells." (PMID 25961925, 2016). "TGF-β1 can promote CCR7/CCL21-mediated crosstalk between tumor cells and LECs, and increase CCR7 expression in EMT cells through p38 mitogen-activated protein kinase (MAPK)-mediated activation of the JunB transcription factor." (PMID 28036019, 2016). "In studies which correlate CCL21 and CCR7 expression, not only the expression level but also the source, tumor cells versus infiltrating immune cells, should also be considered and recorded." (PMID 27369431, 2016). "It was shown that hypoxia induced HIF-1α and HIF-2α expression, which upregulated CCR7; inhibiting HIF-1α or HIF-2α resulted in decreased CCR7 expression and furthermore in inhibition of tumor cell migration and invasion." (PMID 27018053, 2016). "CCR7 expression on tumor cells promotes lymphatic spread in several malignant tumors, although a comprehensive characterization of the CCR7-CCL19/CCL21 axis in LN metastasis still remains to be determined." (PMID 28036019, 2016). "Tumor-infiltrating CD8+ T cells were CD44+, mostly with loss of homing receptors CD62L and CCR7 expression, and composed of two main sub-populations CD45RA− and CD45RA+, suggesting a relatively differentiated status." (PMID 27306834, 2016). "NR1H2/NR1H3 ligands secreted by tumor cells inhibit CCR7 expression on maturing dendritic cells, impairing immune-surveillance and favoring tumor growth." (PMID 26894976, 2016). "C-C chemokine receptor 7 (CCR7) expression levels, the marker of migrating DCs, in spleen DCs and tumor drLN and its ligands C-C motif ligand 19 (CCL19) and CCL21 in spleen were substantially increased by ascophyllan." (PMID 27008707, 2016). "It has been reported that DNA methylation of SMAD4, LEF1, and CCR7 demonstrate varying expression levels (p < 0.05) between tumor and normal samples (MethHC database), which support our results." (PMID 26895224, 2016).